BCL6 (BCL6 transcription repressor)
Diseases named in the same sentence as BCL6 in open-access papers (continued):
Sharing a sentence is not in itself a finding about the gene and the disease.
lymphoma (continued). "For example, in miR-155-induced pre-B cell leukemia/lymphoma, miR-155 directly targets HDAC4 and causes disruption of the HDAC4-BCL6 complex activity, resulting in derepression of BCL6 targets that block B cell development at an immature B cell stage and induce uncontrolled cell proliferation." (PMID 31910827, 2020). "With the deepening of research about BCL6, researchers found that the abnormality of BCL6 expression could be used as the diagnosis marker of GC-derived lymphomas." (PMID 31063496, 2019). "BCL6 is, therefore, an attractive target for therapy in aggressive lymphomas." (PMID 31712669, 2019). "Regions with reduced H3K27Ac associated with Crebbp deletion are enriched for BCL6 target genes, suggesting that CREBBP mutations may in part contribute to lymphoma by eliminating opposition to BCL6-mediated silencing of gene expression." (PMID 31788471, 2019). "In addition, data generated in lymphoma cells derived by murine Bcl6-Rhoh ko Tg mice suggested that RHOH can be involved in DLBCL development by regulating BCL6 expression." (PMID 31248017, 2019). "In addition, gene expression profiling of MYC+BCL2–BCL6+ lymphoma cells has shown them to be different from MYC+BCL2+BCL6– lymphoma cells." (PMID 30323893, 2018). "MYC translocation was more common in BCL-6 translocated lymphomas (p = 0.022)." (PMID 30287880, 2018). "Because BCL6 is required for the survival of certain types of lymphoma, it is also conceivable that BCL6 inhibitors might prove to be useful for MYC/BCL6 DHL." (PMID 30323893, 2018). "In addition, molecular profiling has identified genetic NHL signatures which predict poor prognoses e.g., double-hit lymphomas displaying aberrant expression of Bcl-2, c-Myc, and/or Bcl-6." (PMID 28416758, 2017). "However, there is evidence showing that BCL6 expression in lymphoma is often independent from the corresponding chromosomal alterations, suggesting that mechanisms other than gene rearrangements or mutations can deregulate BCL6 expression in DLBCLs." (PMID 27494852, 2016). "Although BCL6 is known to repress tumor checkpoint genes to support lymphoma cell growth, it could also directly repress BCL2 and BCL2L1 (BCL-XL)." (PMID 26657288, 2016). "From a BCL6 targeted therapeutic approach, this could have the unintended effect of concomitantly inducing pro-survival factors enabling at least a subset of lymphoma cells to survive exposure to RI-BPI or other BCL6 targeted therapies." (PMID 26657288, 2016). "BCL6-targeted therapy kills lymphoma cells by releasing these checkpoints." (PMID 26657288, 2016). "In addition, there is no direct evidence supporting critical oncogenic cooperation between MYC and BCL6 translocation in lymphoma development." (PMID 27347428, 2015). "Thus, we analyzed 46 B-NHL samples with known karyotypes spotted on TMAs for hallmark lymphoma-associated translocations of the IGH-, BCL2, BCL6- and MYC-genes." (PMID 24733537, 2014). "In invasive breast cancer, protein expression of BCL-6 was observed to be associated with cyclin D1 and hypoxia-inducible factor-1-alpha (HIF-1-alpha), first suggesting that BCL-6 oncogene activation plays a role in cancers other than lymphomas." (PMID 25477702, 2014). "Irregularities in the expression of BCL6 may result in aberrant inflammatory responses and the development of various lymphomas." (PMID 25238588, 2014). "Double hit lymphomas involving the BCL6 locus have been reported to be particularly aggressive." (PMID 25349747, 2014). "Gene expression analysis also showed that c-Myc, a possible transcriptional regulator of human U50HG gene, and Bcl6, a transcriptional repressor in relation to translocation in human lymphoma, were detected at similar expression levels in the wild-type and ΔmU50(HG-b) mice." (PMID 23991050, 2013).
lymphoma (continued). "Furthermore, translocations and mutations cause overexpression of oncogenes like BCL2, BCL6 and MYC in lymphoma cells." (PMID 23049692, 2012). "Interestingly IRF4, a tumor suppressor gene in lymphoma and a repressor of BCL6 transcription was methylated in RL cells and down regulated in RL cells and primary FL cells." (PMID 20927367, 2010). "Interestingly, IRF4 is a tumor suppressor gene in lymphoma and functions as a suppressor of BCL6 transcription." (PMID 20927367, 2010). "In our study, rearrangements of the BCL-6 gene at band 3q27 were found in 31% of DLBC lymphomas." (PMID 9184180, 1997). "A study focusing on the Bcl-6-dependent risk stratification of DLBCL based on Peli1 nuclear expression highlighted the potential role of Peli1 and Bcl-6 in assessing DLBCL risk Peli1 expression is highly elevated in high-grade lymphomas but significantly reduced in low-grade lymphomas." (PMID 38179042, 2023). "In addition to COO, chromosomal translocations of BCL6, BCL2, and c-MYC are common cytogenetic abnormalities in DLBCL, and GCB lymphomas harboring these genetic lesions are called “double hit” lymphoma (c-MYC plus BCL2 or BCL6) or triple hit lymphoma (c-MYC plus BCL2 plus BCL6), respectively." (PMID 37566004, 2023). "Moreover, Hodgkin cells may express specific markers of the associated lymphoma (e.g., BCL2/BCL6 for follicular lymphoma and Cyclin D1 for mantle cell lymphoma), sometimes combined with common BCL2/BCL6 or CCND1 rearrangements, respectively." (PMID 36428786, 2022). "However, these prognostic indices do not capture lymphoma related molecular aberrations causing particularly aggressive high-risk disease, such as cell of origin, activated B-cell type DLBCL, MYC and/or BCL2 and/or BCL6 gene re-arranged or double expressor lymphomas." (PMID 35238275, 2022). "Interestingly, AID deficiency reduces the incidence of B lymphomas, but not pre-B lymphomas, whereas this deficiency also prevents GC- and post-GC-derived lymphomas, but not marginal zone lymphoma development, in Iμ Bcl6 transgenic mice." (PMID 34041018, 2021). "Therefore, we speculated that abnormal proliferation of HSCs after BCL6 overexpression in vitro may be similar to the production of lymphoma, which is powered by anaerobic respiration." (PMID 33541426, 2021). "In order to explore whether these changes in gene expression or other aspects of the malignant phenotype might be linked to 3D architectural effects, we performed in situ Hi-C in lymphoma cells collected from involved mesenteric lymph node tumors of moribund Bcl6 (n=3) and Smc3/Bcl6 (n=3) mice." (PMID 34621263, 2021). "However, it is not clear whether BCL6 is required for maintenance, as opposed to development of human DLBCL, and indeed a mouse model shows that transient BCL6 expression at an early stage of development is sufficient to drive development of lymphomas." (PMID 34274316, 2021). "Additionally, Bcl6 is reported to be an oncogene that regulates lymphoma progression." (PMID 32546802, 2020). "Moreover, targeting BCL6 might not only be effective on germinal center derived lymphomas but also those ABC-DLBCL cases that express it41." (PMID 31712669, 2019). "In developing lymphoma cells, this corruption might reflect pre-GC mutations of CREBBP, while in our screen this oncogenic corruption could be provided by the forced expression of BCL2, BCL6, or MYC." (PMID 31586074, 2019). "In their research, hypermethylation of the Bcl6 locus followed by Bcl-6 upregulation, combined with TET2 mutations, was thought to be the key event for lymphoma development which may result in biased Tfh differentiation and eventually contribute to AITL/PTCL development in patients." (PMID 30828337, 2019).
lymphoma (continued). "Thus BCL6 is considered to be involved in germinal center (GC)-derived lymphoma." (PMID 31063496, 2019). "Although our study has focused on the treatment of DHLs with genomic translocation of MYC and BCL2, the concept of simultaneously targeting multi-driver oncogenes may be extended to other DHLs or triple-hit lymphomas (THLs) with genomic abnormalities in BCL6 oncogene." (PMID 31752970, 2019). "Consequently, BCL6 inhibition suppresses lymphoma cells by simultaneously de-repressing multiple genes and delivering a powerful anti-proliferative and pro-apoptotic signal to lymphoma cells." (PMID 26657288, 2016). "The data presented here indicates that in GCB-DLBCL BCL6 inhibitors could serve as crucial building blocks for novel rationally designed combinatorial therapies geared towards more effectively eradicating lymphomas with less toxicity than current chemotherapy-based regimens." (PMID 26657288, 2016). "Thus inhibiting BCL6 is a potential strategy to treat these lymphomas." (PMID 26657288, 2016). "However, MYC/BCL6 DHLs or MYC/BCL2/BCL6 “triple-hit” lymphomas can also occur." (PMID 27606052, 2016). "Epigenetic modulation of BCL6 expression might be effective in germinal center derived lymphomas." (PMID 26682243, 2015). "BCL6 protein has been reported as a master regulator of B lymphocyte development and growth and altered BCL6 protein expression was implicated in pathogenesis of diverse human hematologic malignancies, especially in the diffuse large B cell lymphoma (DLBCL), the most common lymphoma in adults." (PMID 24917186, 2014). "The CD10 negativity, BCL-6 negativity, and EBV positivity may be associated with the poor prognosis of non-GC-type DLBCL, while the KSHV positivity was associated with the extremely low survival rates of 11 patients with KSHV-associated lymphoma." (PMID 24407967, 2014). "In regard to our case, results show a BCL2/BCL6-positive, CD10-faint, CD5/CD23-negative phenotype, suggesting a germinal center-derived lymphoma, likely DLBCL or transformed follicular lymphoma." (PMID 40062071, 2025). "DEL is different from “double-hit lymphoma” (DHL), which refers to lymphoma with BCL2, MYC or BCL6 gene rearrangements, but DEL is also predictive of tumors with high metabolic activity, inhibition of apoptosis, and risk of treatment resistance." (PMID 41229502, 2025). "The patients were divided into groups that differed in the stage of the disease, localization of the lymphoma, and in terms of rearrangements in the MYC, BCL2, and BCL6 genes." (PMID 38861004, 2025). "These mutation patterns indicated divergent evolution of these different lymphomas from a common lymphoma precursor (CLP) cell population, with the FLs and HGBCL‐MYC/BCL2/BCL6 derived from an intermediate subclone of the CLP cell population." (PMID 41047873, 2025). "In contrast, lymphomas with dual MYC and BCL6 rearrangements represent a more diverse group and have variable gene expression profiles and mutational spectra, making them markedly different from DLBCL/HGBL-MYC/BCL2." (PMID 40126346, 2025). "FISH testing is necessary for all large B-cell lymphomas to assess the presence of double-hit or triple-hit lymphoma (high-grade B-cell lymphoma featuring MYC and BCL2 and/or BCL6 rearrangements)." (PMID 40428800, 2025). "Specifically, certain BCL6 FISH probes can misinterpret a single MYC rearrangement as dual oncogenic events by detecting both BCL6 promoter and MYC-BCL6 enhancer rearrangements, thereby inflating triple-hit lymphoma rates." (PMID 41364305, 2025). "Overall, the genesis of lymphomas are due to typical chromosomal rearrangements, most frequently in the oncogenes MYC, BCL2, or BCL6." (PMID 40126346, 2025).
lymphoma (continued). "High-grade B-cell lymphomas with MYC and BCL-2 and/or BCL-6 rearrangements occur in 5% to 10% of DLBCL cases, commonly referred to as double- or triple-hit lymphomas." (PMID 41445799, 2025). "The expression rates of BCL-2, BCL-6, C-MYC, and Ki-67 ≥ 80% were particularly high in patients with complex karyotypes, most of whom were double-expressor lymphomas." (PMID 40696688, 2025). "Using FISH, 23 patients had a BCL2 rearrangement, 28 BCL6, 11 MYC, and seven presented double/triple-hit lymphomas (7.7%)." (PMID 40166656, 2025). "In triple-hit lymphoma (THL), the diagnosis is confirmed with the presence of MYC alongside both BCL2 and BCL6 rearrangements." (PMID 40428800, 2025). "The markers that differentiate these entities include lymphoma markers (e. g., cluster of differentiation [CD] 20, CD79a, BCL2, CD10, BCL6, multiple myeloma oncogene), while in HT, epithelial markers, such as cytokeratin are positive." (PMID 40937371, 2025). "IHC results indicated that the lymphoma cells strongly and diffusely expressed CD10 and BCL-2, with scattered positivity for BCL-6 and CD5, 30% positivity for C-MYC, and negativity for MUM-1." (PMID 40746899, 2025). "These immunophenotypic markers help differentiate it from other aggressive lymphomas, such as diffuse large B-cell lymphoma (DLBCL), which often shows a lower Ki-67 index and variable expression of BCL6 and BCL2." (PMID 41180747, 2025). "Recently, the renewed WHO classification removed BCL-6 from the classification, leaving only rearrangements of MYC and BCL2 to define double-hit lymphomas." (PMID 38397877, 2024). "Double-hit lymphomas (DHL) can be diagnosed by fluorescent in-situ hybridization (FISH), which would reveal translocations of MYC (8q24) and BCL2 (18q21) or/and BCL6 (3q27) in double-hit or triple-hit lymphomas (THL)." (PMID 39449881, 2024). "For lymphoma cells, including DLBCL, BCL6 is a lineage factor, which controls B-cell differentiation, migration (via S1PR), DNA damage response, the cell cycle, and cell death." (PMID 39518937, 2024). "Since by definition, DH/TH lymphomas require the identification of MYC rearrangement, this should be explored first, followed by BCL2 and BCL6 gene study." (PMID 39684922, 2024). "Herein, we report a case of HGBL with MYC, BCL2, BCL6, and CCND1 rearrangements, a so-called quadruple hit lymphoma and describe its molecular and cytogenetic features." (PMID 38914869, 2024). "A double-hit lymphoma is a high-grade B-cell lymphoma (HGBCL) with MYC and BCL2/BCL6 rearrangements." (PMID 39449881, 2024). "Immunohistochemical results of the transformed lymphomas were as follows: CD10, 24% (8/33); Bcl-6, 50% (17/34); MUM1, 65% (20/31); MYC, 30% (6/20); Bcl-2, 79% (27/34); CD5, 32% (9/28); and Ki67 ≥ 60%, 53% (18/34)." (PMID 39460552, 2024). "In this case, the presence of IGH super enhancers (at both joining and switch region) most likely drive constitutive BCL6 and BCL2 transactivation, hence the strong expression of both proteins in lymphoma cells." (PMID 38184753, 2024). "In the revised 4th edition of the WHO Classification (2017), these lymphomas were categorized as HGBL with MYC, BCL2, and/or BCL6 rearrangements." (PMID 38914869, 2024). "This entity is characterized by the presence of MYC and BCL2 and/or BCL6 gene rearrangements and is referred to as HGBL-double-hit (DH)/-triple-hit (TH) and commonly referred to as double-hit (DHL) or triple-hit lymphoma (THL)." (PMID 39038016, 2024). "BCL6 rearrangements, which are found in both ABC and GCB subtypes, can inhibit differentiation and promote survival of lymphoma cells, potentially affecting their radiosensitivity." (PMID 40191738, 2024). "New IHC quantification rules and the joint training with other immunohistochemical biomarkers, such as CD3, CD20, CD5, BCL2, BCL6, Ki67, and MUM1, would be valuable to provide more insights into diagnosis and treatment determination of lymphoma patients." (PMID 38538739, 2024).
lymphoma (continued). "In the previous 2017 WHO classification (WHO-HAEM4), these lymphomas, known as DH or triple-hit (TH) lymphomas, were placed in a provisional category of high-grade B-cell lymphomas with MYC and BCL2 and/or BCL6 rearrangements (HGBCL-DH/TH)." (PMID 39684922, 2024). "Double/triple-hit lymphomas (DHLs/THLs) are an aggressive type of high-grade B-cell lymphomas (HGBLs), characterized by translocations in MYC and BCL2/BCL6." (PMID 37958379, 2023). "WGS analysis additionally identified chromosomal translocations known to be recurrent in lymphoma pathogenesis and relevant for lymphoma subtyping, namely IGH::IRF4 and BCL6 rearrangements." (PMID 37333831, 2023). "BCL6 orchestrates BACH2 protein stability in leukemia and lymphoma, and the BCL6/BACH2 axis equilibrium is crucial for controlling pre-BCR checkpoint cascades." (PMID 36834692, 2023). "The percentage of patients with high-grade lymphoma with gene rearrangements in MYC and BCL2, BCL6, or both was similar." (PMID 37760639, 2023). "Subtype C1 shared alterations in certain pathways (e.g., NOTCH2) with low grade marginal zones lymphomas, and alterations in other NOTCH2 and BCL6 pathways were defining characteristics of this group." (PMID 36818048, 2023). "Further, inhibition of PRMT5 in B cell lymphoma resulted in markedly upregulation of BCL6 target genes, and concomitant inhibition of both BCL6 and PRMT5 exhibited synergistic killing of BCL6‐expressing lymphoma cells." (PMID 37461162, 2023). "Double-hit or Triple-hit lymphoma (DHL/THL) is an uncommon subset of B cell non-Hodgkin lymphoma with recurrent translocations involving MYC/8q24 and BCL2/18q21 and/or BCL6/3q27, according to the 2016 updated WHO classification of lymphoid neoplasias." (PMID 36823603, 2023). "Aggressive lymphomas with an MYC and BCL6 double hit and either DLBCL or HGBL morphology comprise 5 bis 10% of cases." (PMID 37190213, 2023). "Regardless of HGBL-NOS or HGBL with MYC, BCL2 and/or BCL6 rearrangements (double/triple-hit lymphoma), the detection of MYC, BCL2 and BCL6 by FISH is necessary for a clear diagnosis." (PMID 37182167, 2023). "The lymphoma was characterized by a cell-of-origin subtype of germinal center B-cell-like (GCB) based on Hans' classifier (CD10-negative, BCL6-positive, and MUM1-negative); EBER negativity, and the absence of BCL2, BCL6, and MYC rearrangements." (PMID 36975733, 2023). "Once confirmation of a hematolymphoid origin is established with CD45, the ideal IHC lymphoma work up for DLBCL includes CD3, CD20, CD5, CD10, bcl-2, bcl-6, MUM1, cyclin D1, CD30, Ki-67, and Epstein-Barr virus-encoded RNA (EBER) ISH." (PMID 37958219, 2023). "The rapid diagnosis of double/triple-hit lymphomas (DHLs/THLs) involving MYC, BCL2 and/or BCL6 rearrangements is obligatory for optimal patient care." (PMID 37958379, 2023). "Lymphoma material was analyzed regarding COO subtype, MYC, BCL2 and BCL6 expression (by IHC), as well as translocation status (by FISH)." (PMID 35326604, 2022). "For lymphoma tissues, the majority of PCNSLs manifest with low expression of the marker CD10, expression of the marker BCL-6 and high expression of the activated B-cell-like marker MUM-1." (PMID 36596043, 2022). "Lymphomas with chromosomal rearrangements of MYC and BCL2 and/or BCL6 (double- and triple-hit lymphoma, now classified as high-grade lymphoma) are commonly of GCB subtype." (PMID 35305092, 2022). "Double-hit lymphoma is one of the most aggressive and refractory lymphoma subtypes with recurrent genetic abnormalities of MYC and BCL-2 or BCL6 rearrangement, leading to a poor prognosis in the present clinical practice." (PMID 35091546, 2022). "Triple expressor lymphoma is a subgroup of non-Hodgkin's lymphomas that exhibits simultaneous overexpression of the MYC, BCL2, and BCL6 genes." (PMID 36505167, 2022).